SPPL2C (signal peptide peptidase like 2C)
Description:
Sperm-specific intramembrane-cleaving aspartic protease (I-CLiP) that cleaves distinct tail-anchored proteins and SNARE proteins. In elongated spermatids, modulates intracellular Ca(2+) homeostasis by controlling PLN abundance through proteolytic cleavage (By similarity). During spermatogenesis, processes SNARE proteins and impacts vesicular trafficking which supports compartmental reorganization in maturating spermatids and may play a role in formation of the acrosome. In round spermatids, acts as a scaffold protein supporting FREY1 in IZUMO1 recruitment at the endoplasmic reticulum membrane and coordination of IZUMO1 complex assembly. Stabilizes FREY1 at the endoplasmic reticulum membrane through interaction. May recruit IZUMO1 interaction partners.
Synonyms: IMP5
Tractability: Antibody: UniProt predicts a signal peptide or a membrane-spanning region.
Gene: Protein-coding gene on chromosome 17 (45,844,881 to 45,847,067, forward strand). Ensembl gene ENSG00000185294.
Subcellular location: Endoplasmic reticulum membrane
Gene Ontology:
Molecular function: protein binding; protein homodimerization activity; aspartic endopeptidase activity, intramembrane cleaving; aspartic-type endopeptidase activity; molecular adaptor activity
Biological process: membrane protein ectodomain proteolysis; membrane protein intracellular domain proteolysis; acrosome assembly; fusion of sperm to egg plasma membrane involved in single fertilization; intracellular calcium ion homeostasis; membrane protein proteolysis; sperm-egg recognition; protein stabilization; spermatogenesis
Cellular component: cytoplasmic side of endoplasmic reticulum membrane; endoplasmic reticulum membrane; lumenal side of endoplasmic reticulum membrane; Golgi-associated vesicle membrane; lysosomal membrane; membrane
Genetic constraint (gnomAD): Loss-of-function variants: 33 observed, 39.37 expected, observed/expected ratio (o/e) 0.84, 90% interval 0.63 to 1.12. The upper end of that interval is the gene's LOEUF score, 1.12, which puts it in group 4 of 6, group 1 being the genes least tolerant of losing a copy. Missense variants: 895 observed, 920.35 expected, observed/expected ratio (o/e) 0.97, 90% interval 0.92 to 1.03. Synonymous variants: 380 observed, 398.28 expected, observed/expected ratio (o/e) 0.95, 90% interval 0.88 to 1.04.
Homologues: Orthologues: chimpanzee SPPL2C (99% identical), macaque SPPL2C (94% identical), pig SPPL2C (75% identical), rat Sppl2c (71% identical), dog SPPL2C (70% identical), mouse Sppl2c (70% identical), rabbit SPPL2C (69% identical), guinea pig SPPL2C (68% identical). Paralogues in human: SPPL2B (41% identical), SPPL2A (31% identical), SPPL3 (15% identical), HM13 (14% identical).
Diseases named in the same sentence as SPPL2C in open-access papers:
SPPL2C is named in the same sentence as 14 diseases in open-access papers, as found by Europe PMC text mining. Sharing a sentence is not in itself a finding about the gene and the disease. The quoted sentences say what the papers report.
Infertility (3 papers, 2021 to 2023). "Although it is unlikely that disruption of SPPL2C has an effect on intellectual disability, it is possible that its disruption is causative for the infertility described in this patient." (PMID 34089056, 2021). "Since these findings clearly suggested that the normozoospermic infertility of C11orf94−/− males is not related to altered activity of SPPL2c, we analyzed the C11orf94 interactome using an unbiased immunoprecipitation (IP)–MS approach to find alternative pathways in which C11orf94 might be involved." (PMID 35960805, 2022).
COVID-19 (2 papers, 2024 to 2025). A disease caused by infection with severe acute respiratory syndrome coronavirus 2. "Among these overlapping genes, nonsynonymous SNPs in the exons across SPPL2C, CRHR1, MAPT, STH, and KANSL1 genes were identified, among which, 13 were from COVID-19 critical illness and 15 were from COVID-19 hospitalization." (PMID 39764106, 2024).
Parkinson disease (2 papers, 2021 to 2022). A progressive degenerative disorder of the central nervous system characterized by loss of dopamine producing neurons in the substantia nigra and the presence of Lewy bodies in the substantia nigra and locus coeruleus. "Meanwhile, six genes near MAPT in chromosome 17 including MAPT-AS1, SPPL2C, CRHR1, KANSL1, NSF, and WNT3 have been identified as risk genes by earlier GWAS for Parkinson’s disease, another common neurodegenerative disorder which might present clinical symptoms of FTD." (PMID 35509074, 2022).
schizophrenia (2 papers, 2023 to 2026). A major psychotic disorder characterized by abnormalities in the perception or expression of reality. "Representative associations were observed for SPPL2C, MAPT, LRRC37A2, and ARL17A, whose expression in the brain was significantly associated with schizophrenia as well as with MD and λ1 of the right inferior cerebellar peduncle (ICP)." (PMID 41522603, 2026). "In particular, the expression of SPPL2C, MAPT, LRRC37A2, and ARL17A was significantly associated with schizophrenia as well as with MD and λ1 of the right ICP." (PMID 41522603, 2026).
Anxiety (1 paper, 2021). Intense feelings of nervousness, tension, or panic often arise in response to interpersonal stresses. "It is noteworthy that 10 genes (KANSL1-AS1, CRHR1, CRHR1-IT1, SPPL2C, RP11-707O23.5, RP11-259G18.1, MAPT-AS1, LRRC37A4P, PLEKHM1, and DND1P1) showed TWS in both datasets (i.e., PsychENCODE and GTEx), implying these genes are promising candidate genes for anxiety." (PMID 34650599, 2021).
breast carcinoma (1 paper, 2023). "But no previous study has reported the role of PRSS2, SPPL2C and RHBDL1 in breast cancer, thus this study may report the potential role of these genes as independent prognostic predictors in breast cancer for the first time." (PMID 36993976, 2023).
idiopathic interstitial pneumonia (1 paper, 2017). A class of diffuse lung diseases that typically affect the pulmonary interstitium, although some also have a component affecting the airways (for instance, Cryptogenic organizing pneumonitis). "IPF GWAS performed in Japanese and European individuals have identified genetic risk loci within TERT, TOLLIP/MUC5B, and SPPL2C; a GWAS of the broader phenotype idiopathic interstitial pneumonia identified an association within the MUC5B promoter that was also associated with IPF." (PMID 28774304, 2017).
male infertility (1 paper, 2022). The inability of the male to effect fertilization of an ovum after a specified period of unprotected intercourse. "Despite its central position within the found interactive network, loss of SPPL2c does not lead to male infertility, arguing for a potentially redundant function of this protein." (PMID 35960805, 2022).
tumor (1 paper, 2020). "From SPP's participation in tumor progression and survival, to SPPL3's regulation of protein glycosylation and SPPL2c's control over cellular calcium stores, various crossovers between proteolytic activity of intramembrane proteases and cell signaling will be described." (PMID 33381526, 2020).
SPPL2C also shares sentences with these, for which no sentence is quoted: Alzheimer disease (1 paper); frontotemporal dementia (1); Intellectual disability (1); neurodegenerative disease (1); psychiatric disorder (1).